TVP23A (trans-golgi network vesicle protein 23 homolog A)
Synonyms: FAM18A; YDR084C
Tractability: Antibody: UniProt predicts a signal peptide or a membrane-spanning region.
Gene: Protein-coding gene on chromosome 16 (10,760,919 to 10,818,794, reverse strand). Ensembl gene ENSG00000166676.
Subcellular location: Membrane
Subcellular location (Human Protein Atlas): Vesicles
Gene Ontology:
Molecular function: protein binding
Biological process: vesicle-mediated transport
Cellular component: Golgi membrane; membrane
Genetic constraint (gnomAD): Loss-of-function variants: 20 observed, 30.46 expected, observed/expected ratio (o/e) 0.66, 90% interval 0.46 to 0.95. The upper end of that interval is the gene's LOEUF score, 0.95, which puts it in group 4 of 6, group 1 being the genes least tolerant of losing a copy. Missense variants: 278 observed, 254.62 expected, observed/expected ratio (o/e) 1.09, 90% interval 0.99 to 1.21. Synonymous variants: 104 observed, 95.86 expected, observed/expected ratio (o/e) 1.08, 90% interval 0.93 to 1.28.
Homologues: Orthologues: chimpanzee TVP23A (98% identical), macaque TVP23A (96% identical), dog TVP23A (92% identical), guinea pig TVP23A (91% identical), pig TVP23A (91% identical), mouse Tvp23a (88% identical), rat Tvp23a (88% identical), rabbit TVP23A (86% identical), tropical clawed frog tvp23a (71% identical), Drosophila melanogaster CG5021 (46% identical), Caenorhabditis elegans C34D4.4 (32% identical). Paralogues in human: TVP23B (54% identical), TVP23C (52% identical).
Diseases named in the same sentence as TVP23A in open-access papers:
TVP23A is named in the same sentence as 1 disease in open-access papers, as found by Europe PMC text mining. Sharing a sentence is not in itself a finding about the gene and the disease. The quoted sentences say what the papers report.
late-onset Parkinson disease (2 papers, 2023 to 2025). A Parkinson disease that begins after around the age of 50. "Although TVP23A has been reported as a candidate gene for late-onset Parkinson’s disease, its role in amino acid digestibility has not been elucidated." (PMID 40211847, 2025). "Although TVP23A has recently been reported as a candidate gene for late-onset Parkinson’s disease, it has not been described in endometrium-related literature." (PMID 37547609, 2023).